ZEB2 (zinc finger E-box binding homeobox 2)
Diseases named in the same sentence as ZEB2 in open-access papers (continued):
Sharing a sentence is not in itself a finding about the gene and the disease.
tumor (continued). "Moreover, Li and colleagues observed that lncRNA XIST induces tumor metastasis and by Zinc finger E-box-binding homeobox 2 (ZEB2) in NSCLC." (PMID 35453680, 2022). "Additionally, the average tumor weight in the si-circ_0000189 or si-ZEB2 group was observably lower than that in the si-vector group; however, circ_0000189 overexpression increased the tumor weight." (PMID 36193069, 2022). "Therefore, transcriptome analysis of single cancer cells in tumor heterogeneity will be required to demonstrate the possibility as a potential prognostic biomarker of ZEB2 in various cancers including OV." (PMID 35723302, 2022). "The specific internal connection between ZEB2 and interacting genes may be crucial to its role in tumor progression." (PMID 36072677, 2022). "Additionally, the ZEB2:ZEB1 expression alterations in the transient early-activated antiviral CD8 effector cells are similar to the EMT response in some tumours." (PMID 34070208, 2021). "The mRNA level of CXCL12, F3, PHLDA1, and ZEB2 was upregulated in the tumor samples." (PMID 33808801, 2021). "In addition, the suppression of circMMP11 also decreased the protein expression of ZEB2 in dissected tumor tissues." (PMID 33632213, 2021). "In agreement with this hypothesis, co-expression of both Runx1 and Zeb2 in circulating tumor cells has been shown to significantly correlate with cancer reoccurrence." (PMID 34111109, 2021). "In the present study, MALAT1 upregulation in EOC cells was correlated with significantly higher levels of p-PI3K, p-AKT, cyclin D1, vimentin, YAP, and ZEB2, combined with a reduction of E-cadherin expression, thus promoting tumor cell proliferation and metastasis." (PMID 34638541, 2021). "Notably, TBL1XR1 and ZEB2 mutations were enriched in ERG-deleted ALL (present in 21% and 14% of tumours, respectively)." (PMID 34753926, 2021). "Previous studies have described the role of miR-200 family members, including miR-200a, miR-200b, miR-200c, and miR-429-3p in the regulation of expression of the E-cadherin transcriptional repressors ZEB1, ZEB2, and CRKL previously implicated in EMT and tumor metastasis." (PMID 33692799, 2021). "Furthermore, the expression of the ZEB1 and ZEB2 transcription factors, which are promotors of tumour invasion and metastasis, and which are direct targets of hsa-miR-200c-3p, were found to be enhanced in these cells." (PMID 34573283, 2021). "The expression of the circVAPA/miR-342-3p/ZEB2 axis was determined in xenograft tumor tissues." (PMID 34839824, 2021). "Finally, we explored the potential clinical relevance of our findings by analyzing ZEB2 expression in a CRC dataset composed of all fresh frozen tumor samples compiled by the consensus molecular classification consortium." (PMID 31910865, 2020). "In this study we could demonstrate that miR-192-5p acts as a tumor suppressor on EMT through downregulation of ZEB2." (PMID 32630552, 2020). "We also measured the expressions of hsa_circ_0136666, miR-593-3p and ZEB2 in tumor tissues." (PMID 32424109, 2020). "Among them, zinc finger E-box binding homeobox-1 (ZEB1) and -2 (ZEB2) are molecules that play vital roles in signaling pathways to ensure the survival of tumor cells, particularly through enhancing cell proliferation, promoting cell migration and invasion, and triggering drug resistance." (PMID 32664703, 2020). "Hence, ZEB1 and ZEB2 were more frequently expressed in tumor tissue as compared to PT tissue or tissue of CP and HCs." (PMID 32630552, 2020). "All these data suggest that the miR-192-5p/ZEB2 axis may have an important role in the regulation of CTL-mediated tumor immunity, particularly in the context of hypoxic TME." (PMID 33066331, 2020). "RT‐qPCR results showed that, compared with the xenograft tumor zebrafish model group, FH could significantly reduce Snail2, ZEB2, TWIST1, and TGFβ1 mRNA expression (P < .01, 0.05)." (PMID 32037729, 2020).
tumor (continued). "Moreover, miR-144 targets ZEB 1 and ZEB2 and inhibits the invasion of tumor cells, which suggests the role of miR-144 as a tumor suppressor in TC." (PMID 32276343, 2020). "To further investigate the mechanism underlying the tumor suppressive effect of miR-124/miR-203, we knockdowned ZEB2 in 786-O cells by transfecting ZEB2-siRNA or negative control, followed by functional analysis." (PMID 32046742, 2020). "ZEB2 overexpression resulted in up-regulation of pCRAF/pASK1, which subsequently caused increased chemoresistance, enhanced stemness/EMT traits and slowed down the proliferation of tumour xenografts." (PMID 32503256, 2020). "ZEB2 has been found to be a transcriptional repressor of E-cadherin and could promote the epithelial–mesenchymal transition, which contribute to the tumor metastasis and progression." (PMID 30692230, 2019). "Moreover, miR-653 was identified as a tumor suppressor due to its suppression of the ZEB2 expression." (PMID 30979827, 2019). "To delineate whether ZEB2 suppression influenced tumor angiogenesis, we analyzed microvessel density (MVD) in tumors from mouse xenografts." (PMID 29416649, 2018). "ZEB2 can downregulate ephrinB2 through promoter binding to enhance tumor invasiveness." (PMID 29560266, 2018). "Our data found levels of these two miRs to be reduced in the post treatment tumor tissue, and support that ZEB2 would be significantly over-expressed in these cancer cells, which could contribute to tumor metastasis and progression." (PMID 29988972, 2018). "The same study found miR-141 and miR-200 could inhibit ZEB2 (a mediator of tumor cell invasiveness/metastasis)." (PMID 29988972, 2018). "To determine whether miR-454-3p and miR-374b-5p exert tumor suppressive functions in BCa through targetting ZEB2, we designed and conducted rescue assays." (PMID 30352837, 2018). "Both ZEB2 silencing and miR-30a induction resulted in reduced tumor cell migration and halved tail fin invasion, indicating a diminished tumor cell extravasation and distal dissemination." (PMID 29666469, 2018). "MDA231 and MDA157 cells, either silenced for ZEB2 (si1-ZEB2, si2-ZEB2) or ectopically expressing miR-30a (5p/3p), were injected in the yolk sac of zebrafish embryos to monitor tumor cell spreading and in the cardinal vein (duct of Cuvier) to monitor tail fin invasion." (PMID 29666469, 2018). "ZEB2-mediated tumor cell survival and angiogenesis leading to distant organ colonization, may represent a novel pathway via which ZEB2 contributes to distant metastasis." (PMID 29416649, 2018). "The ZEB2 level in the primary tumor vs. metastatic site also needs to be precisely investigated." (PMID 29416649, 2018). "Additionally, PVT1 overexpression also increased the expression of BMI1, ZEB1 and ZEB2 in xenograft tumor derived from 786-O cells." (PMID 29156724, 2017). "The aim of this study was to prospectively validate a gene expression panel (composed of GAPDH, VIL1, CLU, TIMP1, TLN1, LOXL3 and ZEB2) for detecting circulating tumor cells (CTCs) as prognostic and predictive tool in blood samples from 94 metastatic CRC (mCRC) patients." (PMID 28608814, 2017). "Furthermore, with analysis by a real-time qPCR, key transcriptional factors of the EMT such as Snail1, Snail2, Twist1, Twist2, Zeb1, and Zeb2, were found to be markedly expressed in Tg-6m tumor cells when normalized to Tg-3m tumor cells." (PMID 28419107, 2017). "Also, in the animal experiments, PVT1 overexpression increased the expression of BMI1, ZEB1 and ZEB2 in xenograft tumor derived from 786-O cells." (PMID 29156724, 2017). "ZEB2 is a key factor which promotes metastasis in some tumor types." (PMID 27589832, 2016).
tumor (continued). "Our results support the utility of such a combinatorial strategy and specifically point to disruption of ZEB2 function as an attractive therapeutic strategy to inhibit tumour invasiveness and counteract resistance mechanisms that allow tumours to evade anti-angiogenic treatment strategies." (PMID 27470974, 2016). "Importantly, the activation of ZEB2 was accompanied by attenuation of ephrinB2 expression at the tumour rim." (PMID 27470974, 2016). "We next addressed whether inhibiting this pathway by blocking ZEB2 would impede tumour growth and invasiveness in the context of anti-angiogenic therapy." (PMID 27470974, 2016). "Tumour growth was severely reduced (by 83.6%) when ZEB2 was depleted." (PMID 27470974, 2016). "On the basis of our identification of the ZEB2-mediated repression of ephrinB2 as an important step in the control of tumour growth and cell invasion under hypoxia, we next explored whether anti-angiogenic treatment would activate this pathway." (PMID 27470974, 2016). "Notably, ZEB2 silenced tumours appeared highly encapsulated with smooth tumour rims (higher magnifications)." (PMID 27470974, 2016). "Interestingly we observed that miR-203 expression was directly suppressed by ZEB2 via targeting its promoter, which significantly reduced cell migration, invasion, tumor stemness, and chemotherapy resistance in NPC cells." (PMID 27589832, 2016). "We next investigated whether ZEB2 elevation and downregulation of ephrinB2 is a general mechanism utilized in tumour invasion." (PMID 27470974, 2016). "Importantly, inactivation of ZEB2 completely abolished the increased invasiveness induced by bevacizumab and rendered the tumours encapsulated, with smooth margins." (PMID 27470974, 2016). "We observed increased ZEB2 expression in tumor spheres compared to parental NPC cells." (PMID 27589832, 2016). "Thus, We guessed that ZEB2 induced tumor stemness through modulating miR-200/BMI1/SOX2 signals in NPC." (PMID 27589832, 2016). "Moreover, ZEB1 and ZEB2 were significantly higher expressed in HCC tissues than adjacent non-tumor tissues." (PMID 27861158, 2016). "miR-141 and miR-200c, belonging to the highly conserved miR-200 family, whose members are considered as tumor suppressors, can promote the mesenchymal-epithelial transition, and inhibit cell invasion by suppressing the Zeb2 and Snail1 transcriptional repressor complexes." (PMID 27898025, 2016). "The mechanism by which this segregation happens is still unclear and further investigation is needed, but perhaps, co-expression of TWIST1 and ZEB2 could identify patients with undetected tumor spread." (PMID 26214683, 2015). "In addition, a 65% knockdown of ZEB2 in the luciferase-positive human immature-like T-ALL cell line LOUCY resulted in decreased tumour formation when transplanted into NOD/SCID/Il2Rγ null recipients." (PMID 25565005, 2015). "Our immunohistochemical findings provide additional evidences on ZEB2 role in tumor progression." (PMID 26136338, 2015). "In addition, ZEB2 was also reported to upregulate mesenchymal markers, which include N-cadherin and vimentin, as well as facilitate tumor cell invasion." (PMID 25945841, 2015). "Using the TargetScan program, in order to predict candidate miRNAs targeting ZEB genes, that is, miRNAs being able to bind the 3′UTR of ZEB2, they also include in this class of miRNAs miR-141 that resulted to be more expressed in the tumor than in the stroma in our series of cases." (PMID 25143946, 2014). "In addition to FN1 and SPARC, other well-established EMT-associated genes are also upregulated in these tumor samples following letrozole treatment including TWIST1, SNAI2, ZEB1, and ZEB2." (PMID 24944582, 2014). "Thus the mRNA and protein of ZEB2 have contradictory tumor suppressive and oncogenic functions, respectively." (PMID 24523727, 2014). "ZEB2 IHC staining was detected in the cytoplasm and/or nuclei of tumor cells." (PMID 23658743, 2013).
tumor (continued). "EMT is a crucial event in tumor progression, and it is associated with dysregulation of DICER1, E-cadherin and miR-200 family, and upregulation of vimentin, N-cadherin, Twist1, Snail and Zeb2." (PMID 23680357, 2013). "In accordance with previous study, our observations suggest that ZEB2 may act as a tumor suppressor gene in HCC." (PMID 22393452, 2012). "ZEB2 staining was mainly on the cytoplasm and/or nuclei of tumor cells or hepatocytes." (PMID 22393452, 2012). "Therefore, via regulating the expression of E-cadherin by targeting ZEB1 and ZEB2, miR-200a can inhibit the invasive potential of tumor cells." (PMID 22211245, 2012). "Thus, we performed the present large-scale study to investigate the expression dynamics of ZEB2 in tumor and peritumoral liver tissues and its clinicopathologic/prognostic significance in HCC patients using high-throughput TMA and IHC." (PMID 22393452, 2012). "Anyway, since majority of the previous studies was focus on the expression status of ZEB2 in tumor tissues of different human cancers, our data suggested, for the first time, a potential role of ZEB2 expression in peritumoral liver tissues in tumor development of HCC." (PMID 22393452, 2012). "In addition, this work described here is the first to demonstrate TGF-β sensitivity can be partially ameliorated by blocking the expression of ZEB2, a key transcription factor that regulates the progression of tumor cell metastasis." (PMID 21303533, 2011). "In our primary dataset, ZEB1 and ZEB2 were both up-regulated in six out of our eight ccRCC samples and, their expression levels were highly anti-correlated with the miR-200 family in both tumor and normal samples." (PMID 20420713, 2010). "SNAI2, Zeb2 and other family members have multiple gene targets and can recruit specific chromatin-remodelling complexes that repress E-cadherin (CDH1), which is frequently downregulated in tumor progression and EMT and implicated in lymph node metastasis." (PMID 18638373, 2008). "In the tumor cells at metastatic locations, we detected meta-program IV (MAP2, GRIK2), a hallmark of neuron development, and meta-program I, the mesenchymal-neuroblast-like (MES-Nbt) state, which was enriched for genes related to the EMT such as ZEB1, ZEB2, and TEAD1." (PMID 41279557, 2025). "Indeed, we found that despite low general global correlation between mRNA and protein levels that many of the novel markers we identified in our in vitro model were also up-regulated in the tumor resident T cells, including p300, ZEB2, VDR, and many SLC transporters." (PMID 39689157, 2024). "Additionally, in our clones, ZEB1 and ZEB2—transcription factors that attach to the E-cadherin promoter region and inhibit the expression of this adhesion molecule—were upregulated, thereby increasing tumor cell motility." (PMID 35562862, 2022). "Members of the miR-200 family primarily block EMT through direct repression of the EMT inducers ZEB1 and ZEB2, and impede tumor cell dissociation, migration, and invasion, which potentially combats the initial stages of the metastatic cascade, thus implicating the miRNAs’ tumor-suppressive effect." (PMID 35740906, 2022). "Furthermore, ZEB1 promotes tumor growth, whereas ZEB2 reduces tumor aggressiveness in melanomas." (PMID 35805066, 2022). "Thus, PRRX1 is more often positively correlated with ZEB1 and ZEB2 in patients’ HCC tumour samples." (PMID 34496784, 2021). "Mechanistic experiments suggested that circMMP11 exerted its tumor-promoting effects by modulating proliferation, migration, invasion, and apoptosis of BC cells through targeting miR-625-5p/ZEB2 axis, suggesting that circMMP11/miR-625-5p/ZEB2 axis could be used as diagnostic markers for BC." (PMID 33632213, 2021).
tumor (continued). "Further underlining the tight connection between dormancy and chemoresistance, both ZEB2-overexpressing and chemotherapy-treated tumor xenografts acquired increased pCRAF and pASK expression, suggesting that this may represent a common stem in the transition through an EMT/chemoresistant state." (PMID 31910865, 2020). "ZEB2 could act as a transcriptional repressor of E‐cadherin and plays a role in epithelial‐mesenchymal transition, which leads to specific morphological and phenotypic alterations in tumor cells during cancer metastasis." (PMID 32500672, 2020). "We silenced ZEB2 in 786-O cells and found that the proliferation and migration were attenuated, similar to the phenotype observed after miRNA-overexpression in 786-O cells, implying that the tumor suppressive role of miR-124 and miR-203 may be mediated mainly through targeting ZEB2." (PMID 32046742, 2020). "Indeed, tumor buds have been shown to have reduced E‐Cadherin expression, to lose membrane β‐catenin expression and to overexpress EMT associated biomarkers like zinc finger E‐box-binding homeobox 1 and 2 (ZEB1 and ZEB2), SNAIL and N-Cadherin." (PMID 31295960, 2019). "Moreover, ZEB1 and ZEB2 staining were used to detect the EMT in xenografted tumor tissues." (PMID 31429770, 2019). "In addition, ZEB2 elevated mesenchymal markers, as well as facilitated tumor cell invasion." (PMID 30464170, 2018). "Furthermore, ZEB2 induced tumor angiogenesis and circulating tumor cell (CTC) survival in vivo." (PMID 29416649, 2018). "Based on our previous finding that FOXP3 can exert its tumour suppressive activity in part by regulating expression of miR-155, we investigated whether regulation of this microRNA further contributes to the regulation of ZEB2 by FOXP3." (PMID 29963231, 2018). "Thus, interactions between DLEU2, miR-30a-5p and ZEB2 may be biologically significant in the network regulating ccRCC tumor aggressiveness." (PMID 28569782, 2017). "Importantly, silencing of ZEB2 suppresses activation of this mechanism by anti-angiogenic agents, highlighting the HIF-1α–ZEB2–ephrinB2 signalling axis as a potential target for countering tumour cell invasion and overcoming resistance against anti-angiogenic therapies." (PMID 27470974, 2016). "Upon activating TNFR1 on the tumor cells, a phosphorylation of IκB-α on Ser32 and 36 was verified in our study, and such phosphorylation leads to IκB-α degradation, which allows the p50/p65 dimer to enter the nucleus and activate Snail and Zeb2 expression to represse the E-cadherin promoter." (PMID 26318291, 2015). "In addition to being a tumor suppressor, ZEB2 is critical for proper brain development." (PMID 25798919, 2015). "These miRNAs act as tumor suppressors by targeting ZEB1 and ZEB2, key regulators of epithelial-to-mesenchymal transition (EMT) and stemness." (PMID 41011238, 2025). "Tumor specimens exhibited elevated expression of DTX2, SALL1, ZNF93, ZNF146 and ZSCAN16, contrasting with reduced levels of EGR2, GATA2, and ZEB2." (PMID 40647501, 2025). "On one hand, CircZFR binds to miR-377, thereby relieving its suppression of the EMT-related transcription factor ZEB2, which in turn promotes EMT and enhances tumor invasiveness." (PMID 41158508, 2025). "For example, miR-200c, which is frequently downregulated in TNBC, acts as a tumor suppressor by targeting ZEB1 and ZEB2, key regulators of epithelial-to-mesenchymal transition (EMT)." (PMID 41011238, 2025). "It plays an important role in the pathogenesis of several tumor types by targeting ZEB1 and ZEB2, which are transcriptional repressors of E-cadherin, thereby maintaining epithelial integrity." (PMID 41226545, 2025). "WT, Tbx21−/−, or Zeb2−/− KP.SIY lung tumor-bearing mice were treated with MSA-IL2 and MSA-IL12 (alone or in combination) on day 7 of tumor growth and monitored daily for survival." (PMID 41203628, 2025). "The tumor-suppressive effect of miR-192 on specific target genes, such as MYC, XIAP, and ZEB2, is consistent across various cancers." (PMID 40087755, 2025).